RNU6-758P (RNA, U6 small nuclear 758, pseudogene)
Gene: Small nuclear RNA gene on chromosome 16 (75,286,712 to 75,286,800, reverse strand). Ensembl gene ENSG00000252101.
Homologues: Orthologues: macaque U6 (88% identical). Paralogues in human: RNU6-181P (71% identical), RNU6-46P (70% identical), RNU6-1316P (69% identical), RNU6-140P (69% identical), RNU6-20P (69% identical), RNU6-214P (69% identical), RNU6-310P (69% identical), RNU6-434P (69% identical), RNU6-48P (69% identical), RNU6-673P (69% identical), RNU6-686P (69% identical), RNU6-698P (69% identical), and 1281 more.